RAB1C (RAB1C, member RAS oncogene family (pseudogene))
Description:
Protein transport. Probably involved in vesicular traffic (By similarity).
Gene: Processed pseudogene on chromosome 9 (37,636,688 to 37,637,293, reverse strand). Ensembl gene ENSG00000233111.
Subcellular location: Membrane; Cytoplasm
Diseases named in the same sentence as RAB1C in open-access papers:
RAB1C is named in the same sentence as 1 disease in open-access papers, as found by Europe PMC text mining. Sharing a sentence is not in itself a finding about the gene and the disease.
RAB1C shares sentences with these, for which no sentence is quoted: tumor (1 paper).